U3 (Small nucleolar RNA U3 )
Synonyms: LOC124905290
Gene: Small nucleolar RNA gene on chromosome X (72,726,122 to 72,726,337, reverse strand). Ensembl gene ENSG00000273788.
Gene Ontology:
Biological process: RNA processing
Cellular component: nucleolus
Homologues: Orthologues: chimpanzee U3 (98% identical), macaque U3 (91% identical). Paralogues in human: SNORD3P1 (81% identical), U3 (80% identical), U3 (78% identical), SNORD3E (77% identical), SNORD3G (77% identical), SNORD3D (76% identical), U3 (76% identical), U3 (75% identical), U3 (74% identical), SNORD3H (73% identical), U3 (73% identical), U3 (72% identical), and 12 more.